STAT3 (signal transducer and activator of transcription 3)
Diseases named in the same sentence as STAT3 in open-access papers (continued):
Sharing a sentence is not in itself a finding about the gene and the disease.
medulloblastoma (54 papers, 2011 to 2025). A malignant, invasive embryonal neoplasm arising from the cerebellum. "Studies have shown that inactivation of the EGFR/STAT3 signal axis causes cell apoptosis of medulloblastoma." (PMID 39338323, 2024). "In particular, the interleukin-6 (IL6)/gp130/Janus kinase (JAK)/signal transducer and activator of transcription 3 (STAT3) signaling pathway has been implicated in the development of chemoresistance to vincristine in group 3 medulloblastomas." (PMID 37568705, 2023). "STAT3 is a fundamental transcription factor implicated in the proliferation and migration of stem cells, including those of medulloblastoma." (PMID 37106439, 2023). "Phosphorylation of STAT3 was inhibited following sorafenib treatment, which was associated with inhibition of cell proliferation and induction of apoptosis in medulloblastomas." (PMID 26217313, 2015). "To confirm the role of STAT3 in the EMT process in medulloblastoma cells, we performed STAT3 knockdown using STAT3 siRNA and then analyzed the expression of EMT markers in those cells." (PMID 37029430, 2023). "Several studies have recently evaluated STAT3 suppression in OvCa, medulloblastoma, and BrCa using LLL-12." (PMID 37173951, 2023). "We have shown that LLL12B inhibited IL-6-induced STAT3 phosphorylation in human medulloblastoma cells." (PMID 36009550, 2022). "Current studies are underway to examine the effect of STAT3 inhibition on established Shh MB tumor growth and mouse survival to support clinical investigation of STAT3 inhibitors against medulloblastoma." (PMID 34482626, 2022). "In this study, we demonstrate that signal transducer and activator of transcription 3 is critical for Shh signaling and thus is a potential therapeutic target to treat Shh medulloblastoma and overcome drug resistance." (PMID 34482626, 2022). "In this study, we tested LLL12B in human medulloblastoma cells, because medulloblastoma cells are sensitive to STAT3 inhibition." (PMID 33753770, 2021). "Inhibiting STAT3 activity in the medulloblastoma stem cell population would be expected to inhibit tumor progression and the suppressive activity should be further enhanced when in combination with another anti-cancer agent." (PMID 33753770, 2021). "This is evidenced by the knock down of STAT3 by STAT3-specific siRNA can reduce cell viability in medulloblastoma cells." (PMID 33753770, 2021). "Overall, our data provided experimental evidence indicating novel STAT3 inhibitor LLL12B in combination with cisplatin is a potential therapeutic approach for medulloblastoma in the future." (PMID 33753770, 2021). "As a single agent, LLL12B showed an effective inhibition in tumor growth and anti-apoptotic effects through the inhibition of STAT3 signaling in vitro and in vivo in medulloblastoma cells." (PMID 33753770, 2021). "Inhibiting STAT3 using shRNA potentiated the effects of pimozide by inducing autophagy and thereby increasing apoptosis in Daoy medulloblastoma cells." (PMID 32971907, 2020). "Herein, we identify a sex-specific role for the transcription factor Signal Transducer and Activator of Transcription 3 (STAT3) in the Sonic Hedgehog (SHH) medulloblastoma subgroup." (PMID 31683879, 2019). "Segregation of SHH medulloblastoma patients into high and low STAT3 expressing cohorts shows that low STAT3 expression correlates with improved overall survival in male patients." (PMID 31683879, 2019). "In contrast, we observed increased Stat3 expression stochastically distributed throughout SHH medulloblastoma tumors that arise from the granule cell layer." (PMID 31683879, 2019). "Together these data identify STAT3 as a key molecule underpinning the sexual dimorphism in medulloblastoma." (PMID 31683879, 2019). "Here, we show that Axitinib in combination with GDC‐0941 displays enhanced cytotoxic and anti‐proliferative efficacy alongside with a complete abrogation of AKT and STAT3 signalling in c‐myc‐amplified medulloblastoma." (PMID 29377550, 2018).
medulloblastoma (continued). "Aberrant activation of the PI3K/AKT pathway and transcription factor STAT3 is considered critical for medulloblastoma carcinogenesis." (PMID 28159923, 2017). "In keeping with the observed anti-neoplastic capacity we demonstrate that Vandetanib treatment attenuates AKT and STAT3 activity, downstream elements of aberrant signaling pathways in medulloblastoma." (PMID 28159923, 2017). "It was also found that p-SHP2 downregulation was inversely correlated with STAT3 activation in classic but not large-cell medulloblastomas, suggesting differential regulation of STAT3 signaling in the histological subtypes of medulloblastomas." (PMID 28035977, 2016). "Statistical analyses (ANOVA) reveal that the staining densities and the frequencies of p-STAT3 nuclear translocation are significantly different between the three medulloblastoma subtypes and the tumor-surrounding brain tissues (p = 0.000)." (PMID 28035977, 2016). "Our previous results clearly demonstrated that resveratrol can attenuate STAT3 activation of medulloblastoma cells via inhibiting STAT3 transcription and nuclear translocation." (PMID 28035977, 2016). "The results revealed the general reductions of p-SHP2, SOCS3 and especially PIAS3 levels in the three medulloblastoma subtypes with frequent p-STAT3 nuclear translocation." (PMID 28035977, 2016). "Alternatively, it would be more convincing if the levels of SHP2, SOCS1/SOCS3 and/or PIAS3 are altered accordingly in medulloblastoma cells with suppressed STAT3 signaling." (PMID 28035977, 2016). "In this context, it would be worthwhile to elucidate the statuses of STAT3 regulatory factors and their correlations with STAT3 activation in medulloblastomas." (PMID 28035977, 2016). "Taken together, the expression patterns of three STAT3 negative regulators and their correlation with STAT3 activation in human medulloblastomas are investigated in this study." (PMID 28035977, 2016). "In resveratrol-suppressed medulloblastoma cells with STAT3 downregulation and decreased incidence of STAT3 nuclear translocation, PIAS3 is upregulated, the SHP2 level remains unchanged and SOCS3 is downregulated." (PMID 28035977, 2016). "Nevertheless, no comprehensive study is so far available concerning the statuses of those negative regulators in medulloblastoma tissues and their relevance with STAT3 activation." (PMID 28035977, 2016). "Our previous studies demonstrate that STAT3 signaling is the critical molecular target of resveratrol although other signaling pathways are inhibited concurrently in resveratrol-treated medulloblastoma cells." (PMID 28035977, 2016). "Nevertheless, we found that LIF was up-regulated in resveratrol-treated medulloblastoma cells with STAT3 inactivation presumably due to the feedback loop of STAT3 and LIF in those cells." (PMID 28035977, 2016). "A study using resveratrol also reported on the importance of STAT3 signaling in maintenance and survival of medulloblastoma cells." (PMID 25915540, 2015). "Aberrant activation of the transcription factor STAT3 is considered critical for medulloblastoma pathogenesis." (PMID 25596739, 2015). "LY5 selectively inhibits persistent STAT3 activation and induces the apoptosis of medulloblastoma cells and becomes a promising therapeutic drug candidate for human medulloblastoma by inhibiting STAT3 signaling." (PMID 26631279, 2015). "In keeping with these findings the four investigated medulloblastoma cell lines display phosphorylation of Tyr705 of STAT3." (PMID 25596739, 2015). "In keeping with previous reports documenting constitutive STAT3 expression and phosphorylation in human medulloblastoma biopsies, all 4 investigated medulloblastoma cell lines exhibited STAT3 phosphorylation at TYR705." (PMID 25216529, 2014).
medulloblastoma (continued). "Furthermore, we show that Pazopanib attenuates medulloblastoma cell migration a pre-requirement for invasion and that these anti-carcinogenic effects are associated with markedly suppressed phosphorylation of the signal transducer and activator of transcription 3 (STAT3) protein." (PMID 25216529, 2014). "Recently, constitutive STAT3 activation has been documented in primary medulloblastoma tumor samples." (PMID 25216529, 2014). "Moreover, STAT3 activation could be linked to chemoresistence of medulloblastoma cancer stem cells." (PMID 25216529, 2014). "In keeping with these observations, we demonstrated that in the 4 investigated medulloblastoma cell lines, STAT3 protein is expressed and phosphorylated at TYR705." (PMID 25216529, 2014). "In keeping with the observed anti-neoplastic activity of Pazopanib, we also delineate reduced phosphorylation of the STAT3 protein, a key regulator of medulloblastoma proliferation and cell survival." (PMID 25216529, 2014). "For instance, sunitinib (an inhibitor of vascular endothelial growth factor receptor) induces the apoptosis of medulloblastoma tumor cells by inhibiting the STAT3 and Akt signaling pathways." (PMID 25144704, 2014). "The observed suppression of STAT3 phosphorylation is in keeping with the observed proliferation arrest and induction of apoptosis in the analysed medulloblastoma cell lines." (PMID 25216529, 2014). "Knockdown of STAT3 not only downregulated the expression of total and phosphorylated STAT3, but also inhibited the nuclear levels of phosphorylated Rel-A in medulloblastoma cell lines." (PMID 22984561, 2012). "Blocking EFGR significantly inhibited the uPAR and MMP-9 induced EGFR and STAT3 activation in medulloblastoma cells compared to the cells treated with the isotype IgG." (PMID 22984561, 2012). "Our results confirm that uPAR and MMP-9 regulate EGFR/STAT3 regulated signalling pathway in medulloblastoma." (PMID 22984561, 2012). "Our further investigation showed that downregulation of uPAR and MMP-9 inhibited the transcriptional activity of STAT3 in regulating the expression of Bcl-2 and survivin in medulloblastoma." (PMID 22984561, 2012). "Subsequently our antibody blocking experiment confirmed that blocking EGFR inhibited the activation of uPAR/MMP-9 induced STAT3 in medulloblastoma cell lines." (PMID 22984561, 2012). "Sunitinib has been shown to induce apoptosis and growth arrest in medulloblastoma cells by inhibiting Stat3 and Akt signaling pathways." (PMID 22206574, 2011). "Trans-resveratrol rather than its biotransformed monosulfate metabolite exerts anti-medulloblastoma effects by suppressing STAT3 activation." (PMID 22096581, 2011). "Importantly, the present study provided a new rationale for combinational therapies, in which anti-STAT3 small molecule inhibitor is synergistically cooperated with current regimen, cisplatin, in medulloblastoma." (PMID 33753770, 2021). "Besides, in a mouse model of spontaneous medulloblastoma, targeted STAT3 destruction of bone marrow cells altered the presence of CD4 + cell." (PMID 33101383, 2020). "Together these data show that Stat3 is required for SHH signaling and that IL-6 expression is elevated in males which enhances SHH signaling and may contribute to the Stat3 and sex-dependent onset of medulloblastoma." (PMID 31683879, 2019). "This underscores the notion that in medulloblastoma, combined inhibition of both signalling elements STAT3 and AKT might enhance anti‐tumour efficacy." (PMID 29377550, 2018). "However, no report is so far available concerning the statuses of intrinsic STAT3 inhibitory factors in medulloblastomas and the impacts of resveratrol in their expression." (PMID 28035977, 2016).
medulloblastoma (continued). "Therefore, it would be possible that SOCS3 level is reduced in resveratrol-treated medulloblastoma cells with suppressed STAT3 signaling." (PMID 28035977, 2016). "Inverse correlation could be established between p-SHP2 (R = −0.35; p = 0.029), SOCS3 (R = 0.495; p = 0.001) or PIAS3 expression (R = −0.352; p = 0.020) and p-STAT3 nuclear translocation in the classic medulloblastomas." (PMID 28035977, 2016). "SHP2, SOCS3 and PIAS3 are known as the negative regulators of STAT3 signaling, while their relevance to frequent STAT3 activation in medulloblastomas remains unknown." (PMID 28035977, 2016). "PIAS3 upregulation and nuclear translocation in resveratrol-treated medulloblastoma cells with suppressed STAT3 signaling further suggests the negative regulatory effects of PIAS3 on STAT3 signaling and the potential value of PIAS3 in evaluating the prognosis of medulloblastoma patients." (PMID 28035977, 2016). "Because some cancer prognostic factors such as VEGF, Bcl-2 and survivin are the downstream genes of STAT3 signaling, the constitutive STAT3 activation may lead to unfavorable outcomes for the large-cell and classic medulloblastomas." (PMID 28035977, 2016). "Several signaling pathways are known to be involved in the formation and progression of medulloblastomas, of which STAT3 signaling seems most crucial because selective inhibition of STAT3 activation suppresses growth and induces apoptosis of medulloblastoma cells." (PMID 28035977, 2016). "Whether the long-term effects of Pazopanib and Sorafenib on STAT3 protein levels are medulloblastoma-specific or occur as well in other tumor entities will require further evaluation." (PMID 25216529, 2014). "Some authors showed that sorafenib blocks STAT3 (a signal transducer and activator of transcription), as well as the expression of proteins regulating the cell cycle and the apoptosis process, both in cell lines and primary tumor cells of medulloblastoma." (PMID 24559248, 2014). "Taken together, the data from the present study suggest that apoptosis induced in uPAR and MMP-9-downregulated medulloblastoma cells might be due to inactivation of the STAT3-related signaling pathway." (PMID 22984561, 2012). "Similarly our studies showed that by down regulating STAT3 levels in medulloblastoma cells lines, the levels of Rel-A were also reduced." (PMID 22984561, 2012). "Thus, targeting PI3K in combination with pathways signalling via STAT3 might enhance the anti-neoplastic activity and prove therapeutical interest, Yet, whether PI3K/STAT3 crosstalk is a common event in medulloblastoma needs to be further elucidated." (PMID 25596739, 2015). "In keeping with the observed attenuation of migration we detected a marked reduction in STAT3 phosphorylation suggesting that downstream of the MKI targets STAT3, as shown for numerous other cancer types, may be a mediator of cellular migration in medulloblastoma." (PMID 25216529, 2014). "In G3 medulloblastoma, autocrine IL6 signaling activates the STAT3 pathway, contributing to drug resistance; thus, targeting the IL6/STAT3 axis has been proposed as a therapeutic strategy for G3 medulloblastoma." (PMID 39857430, 2025). "RNA sequencing of MEK inhibitor (selumetinib)-treated tumors reveals an upregulation of the JAK/STAT3 pathway, with combinatorial therapeutic strategies of JAK/STAT3 inhibitors and selumetinib investigated for the SHH subgroup of medulloblastoma." (PMID 35835937, 2022). "At present, animal trials have showed an anti-tumor effect of STAT3 inhibitors and CSF1R inhibitors in medulloblastoma." (PMID 35860588, 2022). "In medulloblastoma, SPARC overexpression decreased STAT3 phosphorylation, leading to cell cycle arrest and neuronal differentiation." (PMID 33932101, 2021).
medulloblastoma (continued). "In the present study, we identified a novel small molecular STAT3 inhibitor, LLL12B, and demonstrated that LLL12B inhibits STAT3 phosphorylation and induces apoptosis in medulloblastoma cells in vitro and suppresses tumor growth in vivo." (PMID 33753770, 2021). "The aim of this study is to test the efficacy of a novel STAT3 small molecule inhibitor, LLL12B, in suppressing medulloblastoma cells in vitro and tumor growth in vivo." (PMID 33753770, 2021). "Because LLL12B showed superior in vivo PK and oral bioavailability than its parent STAT3 inhibitor LLL12, we next tested its biological activity to inhibit medulloblastoma cells in vitro and suppress medulloblastoma tumor growth in vivo." (PMID 33753770, 2021). "Further, protein inhibitor of activated STAT3 (PIAS3) has been found to be downregulated in medulloblastomas, and resveratrol shown to significantly upregulate PIAS3 in UW228-2, UW228-3, and DAOY cells with the repression of p-STAT3 levels." (PMID 29495357, 2018). "We exposed the medulloblastoma cell lines for 1 hr to 0.5, 1 and 2 μM and determined the activity of the VEGFR 1/2, PDGFR α/β and c‐kit downstream signalling molecules STAT3 and AKT." (PMID 29377550, 2018). "In line with the enhanced anti-neoplastic effects of the Vandetanib-GDC-combination our findings demonstrate in MYC-amplified medulloblastoma a further reduction in AKT and STAT3 activity respectively in comparison to single drug application." (PMID 28159923, 2017). "In keeping with these findings the four investigated medulloblastoma cell lines showed phosphorylation of serine 472 of AKT and tyrosine 705 of STAT3." (PMID 28159923, 2017). "In MYC-amplified medulloblastoma we also detected a corresponding reduction of AKT and STAT3 phosphorylation and protein levels compared to single drug treatment." (PMID 28159923, 2017). "Multiple factors have been identified as STAT3 signaling promoters, including IL-6 and LIF which are over expressed in medulloblastomas." (PMID 28035977, 2016). "For example, Hh signaling may activate STAT3 activity in transcription-dependent manner via interactions between STAT3 and GLI1 as reported in both the medulloblastoma and granule neuron precursor cells." (PMID 27275540, 2017). "Therefore, the resveratrol-treated medulloblastoma cells would be an ideal model to evaluate the role of SHP2, SOCS3 or PIAS3 in regulating STAT3 signaling." (PMID 28035977, 2016). "Interfering with STAT3 by using a non-peptide small molecule STAT3 inhibitor was reported to decrease cell viability and induce apoptosis in medulloblastoma." (PMID 25915540, 2015). "Here we document for the first time that Pazopanib similar to Sorafenib reduced STAT3 phosphorylation in 3 of 4 medulloblastoma cell lines in a dose- (data not shown) and time-dependent manner." (PMID 25216529, 2014). "In addition, treating pre-established medulloblastoma with siRNAs against uPAR and MMP-9 both alone or in combination with radiation suppressed uPAR, MMP-9, EGFR, STAT3 expression and induced Bak activation leading to apoptosis." (PMID 22984561, 2012). "With the growing functional importance of STAT3 as a transcription factor that modulates cell proliferation and apoptosis, we determined the levels of activated STAT3 in medulloblastoma cells transfected with pU, pM and pUM (with and without radiation)." (PMID 22984561, 2012). "A recent study has shown a relationship among AMBRA1, CUL4–DDB1 complex, and STAT3 in medulloblastoma (MB) stem cells, demonstrating that AMBRA1, through its direct interaction with the CUL4–DDB1 complex, is involved in the degradation of SOCS3, an inhibitor of STAT3 activity." (PMID 37106439, 2023). "Accordingly, combination of targeting of STAT3 pathway using small molecule inhibitors such as LLL12B and cytotoxic chemotherapy may provide improved therapy in medulloblastoma, because, chemo-resistance has been represented a major therapeutic challenge for recurrent medulloblastoma." (PMID 33753770, 2021).
medulloblastoma (continued). "In addition, STAT3 siRNA and LLL12B combination seemed to further inhibit the STAT3 protein and P-STAT3 level but not cell viability, suggesting that cell viability of D425 medulloblastoma cells are not only depend on STAT3 pathway alone." (PMID 33753770, 2021).